CRP (C-reactive protein)
Diseases named in the same sentence as CRP in open-access papers (continued):
Sharing a sentence is not in itself a finding about the gene and the disease.
COVID-19 (continued). "Therefore, in this study, we evaluated whether the circulating levels of TNFR1, TNFR2, and PGRN, in addition to interleukin 6 (IL-6) and CRP, are associated with disease severity and mortality in 80 hospitalized COVID-19 patients." (PMID 36219652, 2022). "•The combination of C-reactive protein ≥ 21 mg/L, hemoglobin < 11.0 g/dL, and lymphopenia < 1500 mm3 on hospital admission and the presence of ground glass ≥ 50% in computer tomography increased the risk of O2 use by 4.97 and 5.33 times respectively in pregnant and postpartum women with COVID-19." (PMID 35767901, 2022). "Additionally, there are studies that have shown the association between COVID-19 severe cases and different biomarkers, such as lymphopenia, thrombocytopenia, D-dimer, serum creatinine, lactate dehydrogenase, C-reactive protein, procalcitonin, creatinine kinase, cardiac troponin, etc.." (PMID 35743751, 2022). "Therefore, the CRP/Alb ratio may be used as a novel and promising predictor for early risk stratification in patients with severe COVID-19." (PMID 34900028, 2021). "Associations between serum lactate dehydrogenase (LDH) levels and DTI metrics have been observed in COVID-19 patients in a 3-month follow-up study, which is in line with our conclusion regarding the associations between microstructural changes in the white matter and CRP." (PMID 34709472, 2021). "Therefore, the CRP/Alb ratio may represent a balance between inflammation and nutritional status, and an increased CRP/Alb ratio may indicate an increased risk of disease progression in patients with severe COVID-19." (PMID 34900028, 2021). "Fifth, the level of CRP may be the marker of the pre-COVID-19 health status of older individuals and illustrates both the burden of chronic diseases -which are mostly risk factors for severe COVID-19- and the inflammaging." (PMID 34506514, 2021). "Elevated CRP, D-Dimer, and interleukin-6 were seen in all three, high ferritin levels in both the strong and the weak, and low lymphocyte counts in the strong and the contributive, whereas high NT-proBNP levels in the contributive and the strong COVID-19-association mortality categories." (PMID 34510338, 2021). "These lines of evidence may suggest that respiratory failure among COVID-19 patients is associated with changes in cytokine profiles, such as over-production of IL-6 and CRP, which can be intensified during the second and mainly the third trimesters of gestation." (PMID 34765620, 2021). "However, the pathogenic role and mechanisms of CRP in COVID-19-associated AKI remain largely unknown." (PMID 33907513, 2021). "Univariate logistic analysis revealed that AKI in COVID-19 patients was associated with older age, history of hypertension, mechanical ventilation, vasoactive drugs, combined treatment with hydroxychloroquine and azithromycin, and higher basal levels of CRP, MCV, leukocytes, neutrophils, and NLR." (PMID 34033655, 2021). "Furthermore, CRP was the mortality predictor, and its expression might be correlated with the formation of ischemia in COVID-19 associated strokes." (PMID 34447386, 2021). "The mechanism underlying the elevated COVID-19 mortality in patients with diabetes may be explained by the increase in chronic inflammatory markers, such as C reactive protein, interleukin 6, interleukin 10, and tumor necrosis factor-α, which promote susceptibility to COVID-19." (PMID 34940517, 2021). "Genetically mimicking IL6R blockade using genetic instruments from the IL6R gene strongly associated with c-reactive protein was associated with lower risk of hospitalized COVID-19, but whether these associations are due to IL-6, IL-6R, or pleiotropic effects via other mechanisms is unclear." (PMID 34163532, 2021).
COVID-19 (continued). "However, further studies with blood sampling from COVID-19 patients should be performed to measure sNRP1 levels and to study the correlation between sNRP1 and COVID-19 risk factors (for example, CRP, d-dimer and IL6) in response to glycemic control in order to elucidate the mechanism." (PMID 34248841, 2021). "Higher levels of inflammatory markers in the blood (such as C-reactive protein and ferritin), an increased neutrophil-to-lymphocyte ratio and increased serum levels of inflammatory cytokines and chemokines have been associated with COVID-19 disease severity and death." (PMID 33995267, 2021). "“CHANeL” prediction models based on serial CRP, neutrophil, and lymphocyte counts during the first 3 days of hospitalization, along with age and hypertension status, provide a reliable estimate of the risk of supplement oxygen requirement among patients hospitalized with COVID-19." (PMID 34158545, 2021). "Thus, there might be a possible virus-associated inflammatory trigger because of elevated CRP level in SARS-CoV-2 infection in these COVID-19 patients." (PMID 35059135, 2021). "Therefore, there is a correlation among elevated acute phase reactants—such as fibrinogen, CRP, and IL-6—which may contribute to COVID-19-associated hypercoagulability." (PMID 33670394, 2021). "The inflammatory marker, CRP, was significantly higher in young males than in young females, suggesting that, at least partly, inflammatory responses might be associated with sex-specific effects of COVID-19." (PMID 33770147, 2021). "Moreover, we analyzed the association of the CRP/PAB ratio with the prognosis for COVID-19." (PMID 34242179, 2021). "Future studies may determine if N/L and CRP have predictive value in the early identification of patients at risk for a more severe COVID-19 phenotype and subsequently most likely to benefit from COVID-19-specific interventions." (PMID 33034239, 2021). "Our data support CRP, a proinflammatory factor implicated in intermittent hypoxia pathways and COVID-19 pathophysiology, as a significant mediator of sleep-related hypoxia and COVID-19 morbidity and mortality, suggesting its role as a relevant intermediary mechanism." (PMID 34757409, 2021). "HRV has previously been used in patients with acute COVID-19 as a noninvasive measure of autonomic function, finding that, after an early increase in parasympathetic activity, patients with elevations of poor prognostic biomarkers, such as CRP (C-reactive protein), exhibited a prior loss of HRV." (PMID 34830716, 2021). "Additionally, severe COVID-19 was associated with increased neutrophil counts (P < .001), C-reactive protein (P < .001), procalcitonin (P = .024) and decreased lymphocyte counts (P = .001), hemoglobin (P < .001), total protein (TP) (P < .001), and albumin (ALB) (P < .001)." (PMID 33157938, 2020). "Studies also revealed that cytokine storm might be one of the main causes of COVID-19 associated death, including the decrease in total lymphocytes and lymphocyte subsets, and the elevation of C-reactive protein, erythrocyte sedimentation rate, serum amyloid, PCT, ferritin, cytokines." (PMID 33308159, 2020). "Insights into CRP structure–function relationships have uncovered both pro- and anti-inflammatory isoforms that may be used to monitor the extent of tissue damage associated with COVID-19 pathologies and prognoses." (PMID 32588812, 2020). "The increased inflammatory marker (CRP) and coagulation marker (d-dimer) levels were also significantly associated with an increased risk of 28-day all-cause mortality of COVID-19 and had interactive effects with cardiac injury markers in predicting the poor outcomes of COVID-19." (PMID 32673499, 2020). "In conclusion, the risk factors for COVID-19 patients to develop from moderate to severe condition consists of: complicated common underlying diseases, respiratory frequency, lymphocyte count, blood glucose, albumin, urea, inflammatory factor (CRP, IL-6), and imaging manifestations." (PMID 33042873, 2020).
COVID-19 (continued). "As determined by the multivariate analysis, CRP (OR 1.026, 95% CI 1.004–1.048, P = 0.018) and lymphocyte proportion (OR 0.924, 95% CI 0.871–0.980, P = 0.009) were significantly associated with the risk of developing severe events in fevered adult COVID-19 patients." (PMID 32719804, 2020). "In the multivariate analysis, patients with headache had lower odds of having increased CRP, abnormal platelet values, lymphopenia and increased D-dimer at the ED visit, and these are factors that are typically associated with the cytokine storm described in COVID-19 patients." (PMID 32727345, 2020). "Systemic inflammatory and coagulation markers, particularly neutrophil percentage, C-reactive protein, D-dimer, and fibrinogen levels, were significantly elevated in the COVID-19 group." (PMID 41827966, 2026). "In unvaccinated subjects, the highest AUROC curve for severe COVID-19 was recorded for CRP (0.668), and in the vaccinated group, the highest was recorded for SII (0.694)." (PMID 41752219, 2026). "AAG seems to represent inflammatory pathways as levels correlate with IL-6 and CRP, specifically NETosis and IL-6 expression, potentially as part of the cytokine storm seen in severe COVID-19." (PMID 41557029, 2026). "CRP demonstrated the highest predictive value for severe COVID-19 (AUC = 0.84), followed by LDH (AUC = 0.80)." (PMID 42213699, 2026). "The C-reactive protein (CRP) concentrations were significantly higher in those with COVID-19 when compared with the PCC patients (p < 0.001)." (PMID 40572294, 2025). "Several proteins linked to the acute phase response, such as CRP, SERPINA3, SAA1 and SAA2, have been shown to increase in the plasma of patients with severe COVID-19 using MS-based data-independent analysis." (PMID 40568587, 2025). "Several studies have revealed elevated CRP levels in severe and fatal COVID-19 patients due to a “cytokine storm,” marked by the excessive release of various pro-inflammatory cytokines." (PMID 41440513, 2025). "Elevated CRP levels were observed in 72 patients (9.4%): 27 (19%) of COVID-19 positives, 3 (11%) of Inf A/B positives, and 42 (7%) of non-ARVIs." (PMID 39998062, 2025). "Several biomarkers have been shown to correlate with the intensity of the inflammatory response in COVID-19: CRP, procalcitonin, IL-6, or serum ferritin." (PMID 39254783, 2025). "CRP levels correlated positively with inflammatory cytokines, particularly IL-6, in COVID-19 patients and served as a biomarker for disease severity." (PMID 40333142, 2025). "Our study also underscores the need for further investigations into the role of serum CRP and D-dimer levels as potential prognostic markers during COVID-19." (PMID 40648912, 2025). "Specifically, we aimed to compare inflammatory markers, including NLR, PLR, dNLR, MLR, LMR, SII, RDW, HLR, HPR, and CRP, between older adults hospitalized with mild COVID-19 and those admitted with other infections." (PMID 41465760, 2025). "Previous studies have described CRP as an important inflammatory biomarker in COVID-19 disease progression, as systemic inflammation is behind the severity of infection." (PMID 40017474, 2025). "CRP is well known for its role in the prognosis of patients with COVID-19 and is a recognized predictor of severe disease progression." (PMID 40141715, 2025). "The available data provide a degree of support for this assumption, with COVID-19 severity correlating directly with C-reactive protein concentrations but inversely with heart rate variability." (PMID 40217761, 2025). "COVID-19 patients also showed higher ferritin, CRP, and urea, and lower platelet and albumin levels (p < 0.001)." (PMID 41286678, 2025). "We termed this score the CARRA-VID score (CRP to Albumin Ratio, Red blood cell distribution width, and age-based score for prognostication of hospitalized COVID-19 patients)." (PMID 40431641, 2025). "Key variables assessed included the albumin/creatinine ratio, age, serum albumin levels, CRP, and history of COVID-19." (PMID 41170570, 2025).
COVID-19 (continued). "Nees (AP) as a potential natural adjunctive therapy for COVID-19, with resulting trends indicating possible benefits in symptom improvement, fever and cough resolution, and reductions in CRP and IL-6 levels." (PMID 40822451, 2025). "AGP, another acute-phase protein, is upregulated in severe COVID-19, and correlates with IL-6 and C-reactive protein levels, underscoring its involvement in cytokine storm pathogenesis." (PMID 40284260, 2025). "Studies on the timing of TCZ application in COVID-19 showed that early TCZ treatment reduces C-reactive protein levels more effectively than standard treatment." (PMID 39955435, 2025). "High levels of CRP, ferritin, D-dimer, AST, ALT, and LDH, among others, have been associated with severe COVID-19." (PMID 40843699, 2025). "An early and temporary inflammatory cytokine response characterized by elevated levels of IFN-γ, GIP-10, IL-6, and C-reactive protein was detected on day 2 after receiving the BNT162b2 mRNA (Pfizer/BioNtech) COVID-19 vaccine." (PMID 40525031, 2025). "Elevated levels of biomarkers such as troponin, D-dimer, C-reactive protein (CRP), B-type natriuretic peptide (BNP), or N-terminal pro-BNP (NT-proBNP) and ferritin have been associated with worse outcomes in COVID-19 patients." (PMID 40002898, 2025). "Compared with controls, COVID-19 patients had markedly higher serum asprosin, ferritin, CRP, and urea levels, while platelet counts and albumin were significantly lower (all p < 0.001)." (PMID 41286678, 2025). "Our results were consistent with findings from nearly all studies in a meta-analysis, which reported significantly lower CRP levels in COVID-19 patients than in influenza patients." (PMID 40142409, 2025). "Consistent with this, serum IL-23 was found to be elevated in all groups of COVID-19 patients with markedly higher values in the critical and severe groups and a significant positive correlation to CRP levels." (PMID 40333142, 2025). "Elevated inflammatory markers (C-reactive protein (CRP), interleukin-6 (IL-6)) and clinical deterioration supported the diagnosis of COVID-19-associated myocarditis." (PMID 41322858, 2025). "Our study reiterates the predictive value of previously identified biomarkers for COVID-19 severity assessment (e.g. age, urea, prothrombin time, c-Reactive protein, and neutrophil-lymphocyte ratio)." (PMID 40065374, 2025). "The results showed that among COVID-19 patients with diabetes, those with older age and higher CRP had significantly higher mortality (adjusted p-value < 0.05), with trends noted for those with higher higher fasting blood glucose (adjusted p-value < 0.1)." (PMID 39886017, 2025). "The inflammatory response in severe COVID-19 mimics bacterial sepsis, with marked elevations in CRP, IL-6, and D-dimers—all markers now widely recognized as diagnostic indicators." (PMID 40284898, 2025). "In 148 patients with COVID-19 an inverse correlation was documented between ChE activity and the inflammatory markers CRP and interleukin-6." (PMID 40299464, 2025). "In our comparison, severe COVID-19 cases were characterized not only by lower vitamin D levels but also by elevated inflammatory markers such as CRP and NLR, which is consistent with previous reports associating these biomarkers with disease severity." (PMID 41301713, 2025). "Infusion of MSCs in severe and critically ill COVID-19 patients resulted in a considerable reduction in levels of CRP, pro-inflammatory cytokines, and NETs, as evidenced by clinical trials." (PMID 40438117, 2025). "Certain vital parameters, biomarkers, and clinical factors have been used as predictors for severe COVID-19 outcomes, including C-reactive protein (CRP), lactate dehydrogenase (LDH), D-dimer, body temperature, and peripheral oxygen saturation (SAT)." (PMID 40238417, 2025). "MR-link-2 also missed one (IL6R instrumented CRP levels and COVID-19) out of three true positives in the drug-target-MR analysis at lenient multiple testing thresholds." (PMID 40610416, 2025).
COVID-19 (continued). "Thomas further confirms the presence of an inflammatory and prothromboticpicture of severe COVID-19 due to high D-dimer and CRP in most of the patients (77 and 69 percent, respectively)." (PMID 41170035, 2025). "LDH and CRP levels, in particular, appear to correlate with respiratory function (PaO2/FiO2) and are established predictors of respiratory failure in COVID-19 patients." (PMID 39849991, 2025). "Elevated inflammatory markers, including erythrocyte sedimentation rate and C-reactive protein, were more prevalent in the surgical group, as was a history of COVID-19, which showed a protective effect (OR = 0.153, P < 0.001)." (PMID 41180631, 2025). "Various blood biomarkers (WBC, CRP, eosinophil, monocytes, platelets etc.)varied since inception of COVID-19 in 2020, world-wide, till date." (PMID 39903736, 2025). "Compared to those with moderate COVID-19, patients with severe disease exhibited elevated levels of procalcitonin, lactate dehydrogenase, ferritin, and C-reactive protein (CRP)." (PMID 40143286, 2025). "A study during the first wave assessed hospitalized COVID-19 patients within one year of discharge and reported significantly higher CRP levels during follow-up in those who developed fibrotic lung changes as compared to non-fibrotic individuals." (PMID 40872813, 2025). "In regard to hematological parameters and inflammation markers (CRP), our findings indicate that the neutrophil count, NLR, and CRP are elevated, while the lymphocyte count is reduced in the COVID-19 ARDS groups compared to the HCs." (PMID 40761632, 2025). "Creatinine, D-dimer, and CRP were in positive correlation with clinical outcome of male COVID-19 and IL-6." (PMID 40868247, 2025). "In a retrospective study of one centre conducted on145 patients with COVID-19, CRP was defined as an earlydetector of disease severity and an adequate biomarker fortherapy planning." (PMID 40386524, 2025). "Multiple studies have confirmed a positive correlation between the severity of COVID-19 and the levels of C-reactive protein (CRP), IL-2, IL-6, IL-7, IL-8, and TNF-α cytokines." (PMID 40371107, 2025). "Other studies also reported increased CRP levels following COVID-19 vaccination among diabetic patients, which they attributed to the pro-inflammatory action of the vaccination." (PMID 40406137, 2025). "The main biological changes observed in hospitalized patients with moderate and severe forms of COVID-19 were the hyperinflammation (CRP, ESR) and hypercoagulation (D-dimers, ferritin)." (PMID 40005449, 2025). "The COVID-19–fungal group showed significantly higher CRP (85.7 vs. 71.6 mg/L, p < 0.001), procalcitonin (2.4 vs. 1.3 ng/mL, p < 0.001), and APACHE II scores (18.6 vs. 14.8, p < 0.001)." (PMID 40299432, 2025). "Studies among adults show that males with COVID-19 had higher neutrophils, CRP, and inflammatory cytokine levels, along with lower lymphocyte levels, which are associated with poor prognosis." (PMID 40283407, 2025). "Patient data, including COVID-19 history, clinical characteristics, and comorbidities, were collected, and laboratory parameters were analyzed, including inflammatory markers like C-reactive protein (CRP) and interleukin 6 (IL-6)." (PMID 41210029, 2025). "The CRP/albumin ratio (CRP/A) emerged as a significant marker in our study for highlighting lung involvement in COVID-19 patients." (PMID 40428888, 2025). "In this observational cohort study of patients with COVID-19-related sepsis, we identified D-dimers, CRP, and lung involvement on CT as independent predictors of unfavorable outcomes." (PMID 40284898, 2025). "This contrasts with the scenario of undifferentiated COVID-19 patients with a full spectrum of disease recently admitted to the hospital, in which CRP had prognostic value, which led to its inclusion in the 4C Mortality score." (PMID 40868809, 2025).